SP1 (Sp1 transcription factor)
Diseases named in the same sentence as SP1 in open-access papers (continued):
Sharing a sentence is not in itself a finding about the gene and the disease.
gastric adenocarcinoma (7 papers, 2005 to 2025). "Bcl-w-stimulated PI3K/Akt signaling also caused Sp1 activation and the resulting increased matrix metalloproteinase-2 expression in gastric adenocarcinoma cell lines." (PMID 22870919, 2012). "Mithramycin is a known chemical inhibitor of Sp1 and we have demonstrated that it reduces cell viability of gastric adenocarcinoma cell lines in a dose and time dependent manner similar to triptolide." (PMID 28192510, 2017). "We have also demonstrated that reduction in levels of Sp1 using mithramycin are associated with a reduction in HSP70 and HSF1, indicating that Sp1 lies upstream of these pro-survival factors in gastric adenocarcinoma cells." (PMID 28192510, 2017). "High levels of Sp1 and HSP70 in resected specimens of gastric adenocarcinoma have been shown to be associated with a poor prognosis." (PMID 28192510, 2017). "Oxidative stress has been shown to increase VEGF production by activating VEGF promotor, located between -449 and -1, in macrophages, or through enhancing the binding of Sp1 and Sp3 transcription factors to proximal GC-rich motifs at -73/-66 and -58/-52 in gastric adenocarcinoma cells." (PMID 27783650, 2016). "In contrast to previous studies that did not identify differences between the 2 histological types, our results reveal that low expression of SP1 is involved in cancer progression and metastasis and differentially affects intestinal-type compared with diffuse-type gastric adenocarcinoma." (PMID 23437057, 2013). "In particular, low expression of SP1 is involved in cancer progression and metastasis and may lead to poor prognosis in intestinal-type gastric adenocarcinoma." (PMID 23437057, 2013). "Our study further demonstrates that triptolide decreases the expression of Sp1 and as a result, HSP70 in two gastric adenocarcinoma cell lines leading to apoptosis." (PMID 28192510, 2017). "A recent report has demonstrated that the oxidative stress incurred by H2O2 increases the VEGF-A gene expression by increasing the binding of transcriptional factors Sp1 and Sp3 to proximal GC-rich motif in AGS human gastric adenocarcinoma cells." (PMID 15811836, 2005).
retinoblastoma (7 papers, 2016 to 2022). A malignant tumor that originates in the nuclear layer of the retina. "It was also described that Curcumin, in retinoblastoma cells, upregulates the expression of 11 miRNAs including miR-22 that leads to a decreased expression of its downstream genes including the transcription factor SP1, implicated in the growth and metastasis of several cancer types." (PMID 27050372, 2016). "In retinoblastoma, LINC00152 is activated by SP1 to inhibit miR-30d and thus regulate the expression of SOX9 and ZEB2 to promote tumor recurrence." (PMID 36033524, 2022). "In retinoblastoma, USP33 was reported to regulate cell proliferation and inhibit apoptosis via stabilizing SP1 and activation of SP1/PI3K/Akt signaling pathway." (PMID 36582601, 2022).
asthma (6 papers, 2021 to 2025). "Both Sp1 and AP-2alpha have been associated with asthma and regulation of asthma related factors." (PMID 38308375, 2024). "It has been argued that ZBTB10's repression of the Sp1 transcription factor, which regulates a number of cytokine-related genes, may account for the association of this gene with asthma." (PMID 39241920, 2024). "Mechanistically, circ-0001875 promoted SP1 translation by competitively binding to miR-31-5p, thereby reducing its inhibitory effect on SP1 translation; SP1 then inhibited M1 macrophage polarization, which is associated with severe asthma, through the NF-κB signaling pathway." (PMID 40661956, 2025). "In this study, OVA-LPS activated the NF-κB signaling pathway in a severe asthma model, and knocking down SP1 further upregulated the expression of NF-κB signaling pathway proteins." (PMID 40661956, 2025). "In our study, we found that SP1 is significantly downregulated in M1 macrophages and PBMCs from patients with asthma, and its expression pattern is similar to that of circ-0001875." (PMID 40661956, 2025). "In order to mimic, in part, the earliest phase of SARS-CoV-2 infection, we stimulated HBECs from asthma patients with SP1." (PMID 34950134, 2021). "Furthermore, SP1 was expressed at low levels in a mouse model of severe asthma, PBMCs from patients with severe asthma, and THP1 cells stimulated with LPS." (PMID 40661956, 2025). "However, whether SP1 expression is modified by dysregulated circRNAs during asthma progression, and the specific mechanisms by which SP1 participates in M1 macrophage polarization, remain unclear." (PMID 40661956, 2025). "In fact, depending on the copy numbers of the Sp1-bing motif in the ALOX5 gene promoter (that can be 5/5, 5/x or x/x, where x differs from 5), the response to montelukast in adults with asthma is known to be different." (PMID 36013002, 2022).
brain tumor (6 papers, 2009 to 2022). "Among the members of the specificity protein (Sp) family, both Sp1 and Sp4 were obviously increased in brain tumor compared with normal brain." (PMID 31717924, 2019). "Our study suggests that Sp1 transcription factor mediates hypoxia-induced ADAM17 expression and proteolytic activity, and contributes to an increase in invasiveness of brain tumor cells under normoxic and hypoxic conditions." (PMID 19772640, 2009). "Our previous studies showed that Sp1 expression is upregulated in high-grade brain tumors, and is significantly higher in TMZ-resistant cells than in parental GBM cells; however, inhibition of Sp1 protein expression restores the inhibitory effects of TMZ in malignant GBM cells." (PMID 32326583, 2020).
fibrosarcoma (6 papers, 2009 to 2023). A malignant mesenchymal fibroblastic neoplasm affecting the soft tissue and bone. "Moreover, in xenograft experiments, the loss of Sp1 in fibrosarcoma cells decreased their ability to form tumors and the role of Sp1 in tumor growth, survival and migration/invasion has been confirmed in other reports." (PMID 26967243, 2016). "Sp1 levels also increase during the process of transformation in a fibrosarcoma transformation model and reducing Sp1 expression in those human transformed fibroblasts inhibits their tumorogenicity." (PMID 19753117, 2009).
latent infection (6 papers, 2008 to 2024). "Collectively, these findings demonstrate that the balance between the repressing and activating roles of each Sp1 site impacts transcriptional noise and the propensity for latent infections." (PMID 19132086, 2009). "This suggests that SP1 may be one of the key players in switching between the latent infection and lytic proliferation." (PMID 18605998, 2008). "It has been recently demonstrated that NFkβ and Sp1 sites present in the HIV-1 LTR influence both, the gene expression levels and the dynamic switching between active or latent infection." (PMID 19607724, 2009). "Thus, viral mutations such as the Sp1 and TATA mutations identified in our study, which result in an increased fraction of viral integrations demonstrating transcriptional delays, could lead to an increase in the fraction of memory T cells that harbor a latent infection." (PMID 23874178, 2013). "Interestingly, we observed reduced expression of Sp1 and Sp1-family transcription factors in differentiated sensory neurons compared to undifferentiated cells, suggesting that reduced Sp1 levels may also contribute to HSV-1 latent infection." (PMID 38349188, 2024).
lymph node metastasis (6 papers, 2015 to 2023). "In addition, SP1 expression was linked with lymph node metastasis (OR = 0.42; 95%CI:0.28-0.64; p < 0.05), advanced TNM stage (OR = 0.34; 95%CI:0.20-0.57; p < 0.05) and infiltration depth (OR = 0.33; 95%CI:0.18-0.60; p < 0.05) which was independent of gender (OR = 1.09; 95%CI:0.88-1.34; p > 0.05)." (PMID 34257529, 2021). "Pearson Chi-square test revealed that Sp1 and COX2 expression were positively associated with lymph node metastasis (P<0.05, both)." (PMID 27057636, 2016). "Down-regulation of miR-335 was found to be significantly associated with lymph node metastasis, invasion of lymphatic vessels, cell invasion and metastasis through targeting of BCL-w and SP1 (specificity protein 1)." (PMID 27322246, 2016). "SP1 low expression was not conducive to lymph node metastasis (OR = 0.42; 95% CI: 0.28-0.64; p < 0.05), progression of TNM stage (OR = 0.34; 95% CI: 0.20-0.57; p < 0.05) and tumor infiltration (OR = 0.33; 95% CI: 0.18-0.60; p < 0.05)." (PMID 34257529, 2021). "Sp1 expression was significantly higher in PDAC cases with lymph node metastasis (P=0.02) than those without lymph node metastasis." (PMID 27057636, 2016). "As previous studies showed, Sp1 and COX2 play a critical role in the pathogenesis, aggressiveness, and angiogenesis of PDAC and their high expression usually indicates the presence of lymph node metastasis, advanced cancer stage, and reduced OS." (PMID 27057636, 2016). "Evidence showed that no matter which separate study was screened out of this analysis, the aggregate estimate of the effect of SP1 expression level on tissue distribution, lymph node metastasis, TNM stage, infiltration and survival time had no significant change." (PMID 34257529, 2021). "However, the overexpression of either SP1 or LOXL2 did not significantly correlate with poor clinical outcomes including lymph node metastasis, depth of invasion, or lymphovascular invasion." (PMID 30976063, 2019).
type 2 diabetes mellitus (6 papers, 2017 to 2025). A type of diabetes mellitus that is characterized by insulin resistance or desensitization and increased blood glucose levels. "These signaling pathways contained the significant gene regulatory network of transcript factors families for type 2 diabetes including SP1, NFIC, ZFP161, and FOS, JUND, JUNB." (PMID 28179884, 2017). "Increased NF-κB activation in type II diabetes mellitus has also been implicated in impaired vascular function, including myogenic tone, vascular reactivity, and inflammatory response through the detection of PARP-1, SP-1, and COX-2 activity." (PMID 40649025, 2025). "In mice with type 2 diabetes mellitus (T2DM), increased fatty acid levels downregulate SP1 expression." (PMID 33328993, 2020).
acute lymphoblastic leukemia (5 papers, 2017 to 2023). Leukemia with an acute onset, characterized by the presence of lymphoblasts in the bone marrow and the peripheral blood. "For example, in acute lymphocytic leukemia T cells, overexpression of the IL1A nuclear propeptide has been demonstrated to promote proliferation and reduce apoptosis, by NFkB and SP1 up-regulation." (PMID 34997006, 2022). "In acute lymphoblastic leukemia (ALL), hypermethylation of the AHR promoter was found in 33% of patients and impaired binding of SP1 resulting in AHR transcriptional silencing." (PMID 37696456, 2023).
cognitive deficits (5 papers, 2019 to 2025). "SP1 has a dramatic elevation in AD and is associated with cognitive deficits, inflammation, and neuronal survival." (PMID 35150479, 2022). "Increased TGF-β1 leads to elevated Smad2/3 phosphorylation resulting in the Smad2/3 then translocation into the nucleus, enhancing the activity of the transcription factor Sp1, which mediates synaptic and cognitive deficits." (PMID 40425782, 2025). "Sp1 is predominantly expressed by astrocytes, and Sp1 knockout impairs neuronal outgrowth and alters astrocyte morphology accompanied by cognitive deficits." (PMID 39702695, 2025). "Increased TGF-β1 promotes the phosphorylation and nuclear translocation of Smad2/3, sequentially activating the transcription of Sp1, which is regarded as a key feature of AngII-induced synaptic and cognitive impairments." (PMID 40425782, 2025). "Consistent with this, our findings demonstrate that Sp1 knockdown reversed the cognitive impairments induced by TGF-β1." (PMID 40425782, 2025). "Collectively, these findings strongly support the hypothesis that TGF-β1-upregulated Sp1 mediates synaptic and cognitive impairments." (PMID 40425782, 2025). "This occurs as the result of increased TGF-β1 that upregulates the phosphorylation of Smad2/3, which then leads to the nuclear translocation of Smad complex may trigger the transcription of Sp1 and ultimately leading to synaptic damage and cognitive impairments." (PMID 40425782, 2025). "Conversely, Sp1 overexpression in wild-type rats led to severe synaptic dysfunction in the hippocampal CA1 region, and consequently, cognitive deficits." (PMID 40425782, 2025).
diabetic retinopathy (5 papers, 2019 to 2023). "According to earlier research, specificity protein 1 (SP1) enhances the binding to the ROBO4 promoter, increasing Robo4 expression and hastening the progression of diabetic retinopathy." (PMID 37430272, 2023). "Moreover, SP1 regulates the expression of the RGC‐specific gene syt11,42 and its expression is upregulated in the RGCs of patients with diabetic retinopathy." (PMID 32562344, 2020).
epilepsy (5 papers, 2012 to 2024). A brain disorder characterized by episodes of abnormally increased neuronal discharge resulting in transient episodes of sensory or motor neurological dysfunction, or psychic dysfunction. "Recent molecular studies showed that SP1 plays a role in epilepsy, neuronal injury, and maintenance of spontaneous seizure activity." (PMID 38467626, 2024). "The most common analgesic/antipyretic medicine, APAP, can induce AMFR transcriptional activation via SP1 and exerted an antiepileptic effect in mouse models of epilepsy." (PMID 35938532, 2022). "SP1 has a long-lasting increased activity in kainate-induced epilepsy model, and neonatal epilepsy-associated KCNQ2 and KCNQ3 genes are activated by SP1." (PMID 23189039, 2012). "The IR in control tissues was sporadic, further supporting SP1 potential role in ECM in epilepsy." (PMID 38467626, 2024).
fibrosis (5 papers, 2013 to 2025). the formation of excess fibrous connective tissue in an organ or tissue in a reparative or reactive process. "Previous studies showed that singly spliced HBV SP1 RNA generated the expression of HBSP, which was linked to an increased risk of the development of HCC by promoting viral replication, protein production and liver fibrosis." (PMID 34903774, 2021).
Insulin resistance (5 papers, 2014 to 2026). Increased resistance towards insulin, that is, diminished effectiveness of insulin in reducing blood glucose levels. "Thus, the O-GlcNAc modification of proteins bound to promoters, including Sp1, is linked to adipocytokine transcription during insulin resistance." (PMID 25657638, 2014). "Future work is aimed at identifying the specific function of the O-GlcNAc modification on Sp1 during insulin resistance in adipocytes." (PMID 25657638, 2014). "After determining that Sp1 was a common cis-acting motif for these genes, we found that the O-GlcNAc modification of Sp1 trended toward an increased level during insulin resistance in mouse adipocytes." (PMID 25657638, 2014). "Since these sites are reported to be important for transcriptional activation, we wanted to determine whether Sp1 and O-GlcNAc modified proteins were enriched at these sites during insulin resistance in 3T3-F442a adipocytes." (PMID 25657638, 2014). "We determine that Sp1 is more heavily O-GlcNAc modified during insulin resistance." (PMID 25657638, 2014). "Furthermore, we show that the LPL and SPARC promoters are enriched for Sp1 and O-GlcNAc modified proteins during insulin resistance in adipocytes." (PMID 25657638, 2014).
keloid (5 papers, 2014 to 2025). An irregularly shaped, elevated mark on the skin caused by deposits of excessive amounts of collagen during wound healing. "SP1 as a potent inducer of extracellular matrix expression by fibroblasts, is a well-known TF involvement of keloid pathogenesis mainly by regulation of the extracellular matrix." (PMID 34600545, 2021). "The addition of phosphatidylinositol 3-kinase (PI3K), mitogen activation protein kinase (MAPK), Specificity protein 1 (Sp1), and mammalian target of rapamycin (mTOR) inhibitors inhibited IL-18 secretion in keloid cocultures, suggesting their potential clinical use in the treatment of keloid." (PMID 39799030, 2025). "The downregulation of FOXF1 and LPAR1 in keloid patients could be caused by the inactivation of E2F1 and SP1 due to mutations or other factors, or by the effect of the three miRNAs." (PMID 38444850, 2024). "GNG13, ADCY8, NPY and HTR1A may act as core genes in keloid formation and these core genes establish relationship with SP1 and miRNA (hsa-mir-372, hsa-mir-20, hsa-mir-10b), which may influence multiple signaling pathways in the pathogenesis of keloid." (PMID 34600545, 2021). "Because TGF-β is widely regarded as the central progenitor of fibrotic scars and has a large capacity for autocrine signaling, the degradation of Sp1 may serve as a putative pharmacological target in keloids." (PMID 25328513, 2014). "Furthermore, nine core miRNAs (hsa-mir-124, hsa-let-7, hsa-mir-155, hsa-mir-26a, hsa-mir-941, hsa-mir-10b, hsa-mir-20, hsa-mir-31 and hsa-mir-372), and two core TFs (SP1 and TERT) were identified to play important roles in keloid formation." (PMID 34600545, 2021).
lung fibrosis (5 papers, 2013 to 2026). "The nuclear transcription factors which are blocked by col(V) treatment and implicated in pulmonary fibrosis are NF-κB, Sp1 and CCAAT/enhancer-binding protein β (Cebpb), SNAIL and STAT6." (PMID 24204629, 2013). "Targeting basal cell dysfunction or SP1-related pathways may offer new therapeutic opportunities for idiopathic pulmonary fibrosis." (PMID 42252704, 2026).
lymphoma (5 papers, 2017 to 2021). A malignant (clonal) proliferation of B- lymphocytes or T- lymphocytes which involves the lymph nodes, bone marrow and/or extranodal sites. "In lymphoma, SIOMICS found four motifs similar to the motifs of SP1, MAZ, GC and the CAC-binding protein, respectively." (PMID 28684851, 2017). "Patients with SS and lymphoma expressed SSA, SSB and anti-SP1 together." (PMID 34249010, 2021). "Moreover, the expression of LIGHT was triggered by inducing Sp1 transcriptional activation in response to Axl signaling in Jurkat cells, providing evidence that Sp1 activation was required for Axl-induced LIGHT expression in T lymphoma." (PMID 28423548, 2017).
meningioma (5 papers, 2020 to 2025). A generally slow growing tumor attached to the dura mater. "Interaction with SP1 may exert additional regulatory effects on gene transcription and signalling; high SP1 expression in meningiomas has been associated with tumour grade and malignancy, suggesting a possible prognostic biomarker role." (PMID 41009755, 2025). "Moreover, the abnormal expression of SP1 is also associated with the recurrence of meningioma." (PMID 37041519, 2023). "Likewise, high p40 and SP1 expression was associated with poor RFS but no associated with OS of meningioma patients." (PMID 38758750, 2024). "Furthermore, radiation treatment was found to recruit SP1 transcription factor in meningioma cells." (PMID 32046773, 2020).